LHX5 (LIM homeobox 5)
Description:
Plays an essential role in the regulation of neuronal differentiation and migration during development of the central nervous system.
Tractability: No criterion of Open Targets' tractability assessment is met for any kind of drug.
Gene: Protein-coding gene on chromosome 12 (113,462,033 to 113,472,280, reverse strand). Ensembl gene ENSG00000089116.
Subcellular location: Nucleus
Subcellular location (Human Protein Atlas): Cytosol; Nuclear bodies; Nucleoplasm
Gene Ontology:
Molecular function: protein binding; sequence-specific double-stranded DNA binding; DNA-binding transcription factor activity, RNA polymerase II-specific; RNA polymerase II transcription regulatory region sequence-specific DNA binding; DNA binding; sequence-specific DNA binding; zinc ion binding
Biological process: neuron differentiation; regulation of transcription by RNA polymerase II; positive regulation of DNA-templated transcription; regulation of DNA-templated transcription; spinal cord association neuron differentiation
Cellular component: chromatin; nucleus
Genetic constraint (gnomAD): Loss-of-function variants: 6 observed, 28.18 expected, observed/expected ratio (o/e) 0.21, 90% interval 0.12 to 0.42. The upper end of that interval is the gene's LOEUF score, 0.42, which puts it in group 1 of 6, group 1 being the genes least tolerant of losing a copy. Missense variants: 458 observed, 516.07 expected, observed/expected ratio (o/e) 0.89, 90% interval 0.82 to 0.96. Synonymous variants: 266 observed, 231.83 expected, observed/expected ratio (o/e) 1.15, 90% interval 1.04 to 1.27.
Homologues: Orthologues: chimpanzee LHX5 (100% identical), macaque LHX5 (99% identical), mouse Lhx5 (99% identical), pig LHX5 (99% identical), rat Lhx5 (99% identical), dog LHX5 (98% identical), rabbit LHX5 (98% identical), guinea pig LHX5 (88% identical), tropical clawed frog lhx5 (86% identical). Paralogues in human: LHX1 (75% identical), LHX3 (37% identical), LHX4 (35% identical), ZFHX3 (29% identical), ZFHX4 (28% identical), LMX1B (27% identical), LMX1A (27% identical), LHX2 (25% identical), LHX6 (24% identical), LHX8 (23% identical), LHX9 (23% identical), ZFHX2 (21% identical), and 8 more.
Diseases named in the same sentence as LHX5 in open-access papers:
LHX5 is named in the same sentence as 20 diseases in open-access papers, as found by Europe PMC text mining. Sharing a sentence is not in itself a finding about the gene and the disease. The quoted sentences say what the papers report.
breast carcinoma (2 papers, 2017 to 2020). "LHX5 has been reported to have prognostic value in breast cancer." (PMID 32158343, 2020). "A previous study reported that LHX5 was found to have prognostic value; independent of the sub-types and other clinical factors in breast cancer." (PMID 32158343, 2020).
schizophrenia (2 papers, 2010). A major psychotic disorder characterized by abnormalities in the perception or expression of reality. "Two other CNS-related candidate genes, CEBPD and LHX5 may be associated with schizophrenia, but the results of array CGH should be treated carefully in the absence of validation by other technologies." (PMID 20064257, 2010).
urothelial carcinoma of the bladder (2 papers, 2020 to 2021). "LHX5 expression is significantly associated with the tumour grade (low/high grade) of urothelial carcinoma of the bladder." (PMID 32158343, 2020). "However, there was a significant association between the expression of LHX5 with the tumour grade (low/high grade) of urothelial carcinoma of the bladder." (PMID 32158343, 2020). "The present study is the first study characterising LHX5 protein in urothelial carcinoma of the bladder." (PMID 32158343, 2020). "ISL1 and LHX5 expression was found across all tumour grades and stages of urothelial carcinoma of the bladder." (PMID 32158343, 2020). "Dysregulated LHX5 has also been observed in urothelial carcinoma of the bladder." (PMID 34238116, 2021). "However, further functional studies of the protein need to be done to confirm the functional significance of the expression and role of ISL1 and LHX5 in urothelial carcinoma of the bladder." (PMID 32158343, 2020).
glioblastoma multiforme (1 paper, 2025). "LHX5, one of the top-ranked upregulated genes, was associated with the prognosis of glioblastoma multiforme." (PMID 41007824, 2025).
glioma (1 paper, 2021). A benign or malignant brain and spinal cord tumor that arises from glial cells (astrocytes, oligodendrocytes, ependymal cells). "A series of genes such as EN1, S100A4, ANXA1, PDPN, IGFBP2 and CHI3L1 were upregulated in radiotherapy treated glioma patients, while other genes such as PRLHR, SFRP2, BRINP1, TRIM67, LHX5, KCNIP2 and NSG2 were downregulated." (PMID 34852024, 2021).
Urothelial Carcinoma of the (1 paper, 2020). "In general, the immunohistochemical protein expression characteristics of ISL1 and LHX5 reflect their potential roles in urothelial carcinoma of the bladder tumourigenesis." (PMID 32158343, 2020). "A total of 100 formalin-fixed paraffin-embedded urothelial carcinoma tissues were selected from the Department of Pathology, Hospital Kuala Lumpur and the protein expression of ISL1 and LHX5 was determined using immunohistochemistry." (PMID 32158343, 2020).
cancer (2 papers, 2020 to 2021). A tumor composed of atypical neoplastic, often pleomorphic cells that invade other tissues. "The expression pattern of Islet-1 (ISL1) and LIM homeobox 5 (LHX5) across different cancer stages and grades, as well as the association between the protein expression of these genes and patient demographics and clinicopathological features, were examined." (PMID 32158343, 2020). "Based on the evidence that LHX5 and TLX1 have the potential to promote neuronal differentiation, we speculated that they may also be linked to cancer stemness and recurrence of GBM." (PMID 34238116, 2021). "To date, there have been few studies characterising the role of LHX5 in cancer." (PMID 32158343, 2020). "There were no distinct LHX5 expression patterns associated with different cancer stages, but the proportion of high-expressing tumours was higher in high-grade tumours." (PMID 32158343, 2020). "Although there were no previous studies that examined the expression of LHX5 in cancer tissues, one study conducted in rats, discovered nuclear staining of LHX5 in cajal-retzius cells; the first neuronal cell type in mammalian telencephalon." (PMID 32158343, 2020).
tumor (2 papers, 2017 to 2020). "In addition, there was a significant association between the expression of LHX5 and tumour grade." (PMID 32158343, 2020). "There was a greater percentage of high LHX5-expressing tumours in high grade tumours as compared to low grade tumours." (PMID 32158343, 2020). "In this study, there was a lower proportion of high LHX5-expressing tumours in stage 3 and stage 4 tumours as compared to stage 1 and stage 2 tumours; perhaps indicating a more pronounced role during the earlier stages of tumourigenesis." (PMID 32158343, 2020). "The highest percentage of high LHX5-expressing tumours were stage 1 tumours and grade 2 tumours." (PMID 32158343, 2020). "The high percentage of tumours expressing both these genes suggests that ISL1 and LHX5 play an important role in bladder tumourigenesis across multiple stages." (PMID 32158343, 2020). "In contrast, there was no distinct trends observed in the expression of LHX5 based on the tumour stage and grade." (PMID 32158343, 2020). "The lack of correlation in clinicopathological parameters and patient demographics suggest that ISL1 and LHX5 may not be suitable prognostic markers for tumour progression because the expression is relatively high in a significant subset of tumours." (PMID 32158343, 2020).
LHX5 also shares sentences with these, for which no sentence is quoted: Ataxia (2 papers); epilepsy (2); neurodevelopmental disorder (2); acute lymphoblastic leukemia (1); cervical cancer (1); chronic myeloid leukemia (1); clear cell renal cell carcinoma (1); follicular lymphoma (1); head and neck squamous cell carcinoma (1); microphthalmia (1); Nephroblastoma (1); ovarian carcinoma (1).